MAP3K7 (mitogen-activated protein kinase kinase kinase 7)
Diseases named in the same sentence as MAP3K7 in open-access papers (continued):
Sharing a sentence is not in itself a finding about the gene and the disease.
parasitic infections (1 paper, 2025). "In chronic gastrointestinal helminth burdens, MAP3K7-binding protein 2, a downstream effector of MAP3K7 signaling, was positively correlated with parasite burden, indicating its involvement in modulating host responses to parasitic infections." (PMID 40150341, 2025). "The MAP3K7 gene, also known as Transforming growth factor b-activated kinase 1 (TAK1), emerges as a crucial regulator of immune responses against parasitic infections in sheep." (PMID 40150341, 2025).
peripheral T cell lymphoma (1 paper, 2024). "Our study revealed that the expression of specific genes, including TNFRSF1B, TRADD2, and MAP3K7, may play an important role in chemotherapy resistance in peripheral T-cell lymphoma." (PMID 38468267, 2024). "This groundbreaking discovery suggests that the expression patterns of multiple genes, particularly TRADD2 and MAP3K7, may play a crucial role in chemotherapy resistance in peripheral T-cell lymphoma (PTCL)." (PMID 38468267, 2024). "In addition, phosphatidylinositol-4,5-bisphosphate 3-kinase catalytic subunit delta (PIK3CD), mitogen-activated protein kinase kinase kinase 7 (MAP3K7) and mitogen-activated protein kinase kinase 6 (MAP2K6) are downregulated in peripheral T-cell lymphoma during chemotherapy resistance." (PMID 38468267, 2024).
prostatic intraepithelial neoplasia (1 paper, 2023). "In contrast, MAP3K7-depleted grafts displayed a mixture of benign, high-grade prostatic intraepithelial neoplasia (PIN), and carcinoma phenotypes." (PMID 36776288, 2023).
Refractory anemia (1 paper, 2022). "The expression levels of ABCB7 and MAP3K7 were compared among SF3B1WT-, SF3B1K700E-, and SF3B1non-K700E-MDS patients in both whole cohort and subgroups (Refractory anemia [RA] and RA with ring sideroblasts [RARS])." (PMID 36028755, 2022).
Sepsis (1 paper, 2020). Sepsis is defined as life-threatening organ dysfunction caused by a dysregulated host response to infection. "Compared with infection patients and healthy controls, PBMC from sepsis patients also had higher levels of mitogen-activated kinase kinase kinase 7 (MAP3K7), a known target protein of miR-10a and an activator of the NF-κB pathway." (PMID 32214905, 2020). "In the present study, MAP3K7 levels in PBMC were elevated in sepsis patients and diminished in THP-1 cells overexpressing miR-10a, supporting that MAP3K7 is a target of miR-10a in immune cells." (PMID 32214905, 2020). "Levels of MAP3K7 from sepsis patients were significantly higher than those of infection patients and healthy controls." (PMID 32214905, 2020).
tauopathy (1 paper, 2021). Neurodegenerative disorders involving deposition of abnormal tau protein isoforms (tau proteins) in neurons and glial cells in the brain. "Problem 2 asked participants to predict compounds that bind the Tauopathy pro-targets AURKA, PAK1, FGFR1, and STK11 and avoid the Tauopathy anti-targets PAK3, MAP3K7, and PIK3CA." (PMID 34520464, 2021). "Problem 2 asked participants to predict compounds that bound the Tauopathy pro-targets, AURKA, PAK1, FGFR1, and STK11 and did not bind PAK3, MAP3K7, and PIK3CA." (PMID 34520464, 2021).
ulcerative colitis (1 paper, 2020). An inflammatory bowel disease involving the mucosal surface of the large intestine and rectum. "Furthermore, single nucleotide polymorphisms (SNPs) in the TAK1-TNF pathway including MAP3K7 and TNFSF18 (Crohn's disease), TNFSF14 and 16NFKB1 (ulcerative colitis), TRAF3IP2 and TNFAIP2 (general inflammatory bowel disorder) are associated with higher risk for disease development." (PMID 32873150, 2020).
ZIKV infection (1 paper, 2017). "The inflammatory profile is partially different following ZIKV infection, which is mainly characterized by less inflammatory response and by the specific induction of several MAPK genes (MAP2K1, MAP2K3, MAP3K7, MAPK1, MAPK3)." (PMID 28873445, 2017).
tumor (47 papers, 2011 to 2026). "MAP3K1 is involved in the survival and migration of tumor cells, and MAP3K7 is an important regulator of cell pathways associated with cell proliferation in cancer." (PMID 34638557, 2021). "PCAT‐1 knockdown eliminated the tumour‐promoting effect caused by miR‐129 inhibition, probably through repressing MAP3K7 and subsequent NF‐κB activation." (PMID 32048803, 2020). "In our present study, MAP3K7 expression was much higher in tumor tissues than in adjacent normal tissues and was associated with poor survival of HCC patients." (PMID 31214512, 2019). "Similarly, elevated expression of MAP3K7 has been associated with tumor progression and reduced survival in CRC patients." (PMID 39901302, 2025). "Furthermore, loss of Map3k7 in mice has been shown to promote prostate tumorigenesis, suggesting MAP3K7 plays a tumor-suppressive function in the prostate." (PMID 32630372, 2020). "MAP3K7 is overexpressed in tumor tissues and is associated with poor survival." (PMID 31387297, 2019). "We discover that loss of CHD1 and MAP3K7 (encoding TAK1) potentiates the transcriptional response to IFN-γ, thereby creating an acquired vulnerability by sensitizing cancer cells to tumor-reactive T cells." (PMID 41564866, 2026). "Another example is the co-loss of MAP3K7 and CHD1, two tumor suppressor genes, which coordinate to drive disease aggressiveness." (PMID 40840524, 2025). "Based on data from pancreatic organoids and cell lines, we further suggest that SF3B1K700E promotes PDAC progression by reducing tumor-suppressive TGF-β signalling through missplicing of MAP3K7." (PMID 37823551, 2023). "Meanwhile, PCAT-1 knockdown prevented the tumor progression when miR-129 was inhibited, potentially achieved by suppressing Mitogen-activated protein kinase kinase kinase 7 (MAP3K7) expression and activating Nuclear factor-kappa B (NF-κB)." (PMID 37987364, 2023). "An FISH probe for MAP3K7 had been selected for this study because of its location in the center of the 6q15 deletion and the known tumor suppressive function of MAP3K7." (PMID 34625909, 2022). "In this investigation, it was observed that MAP3K1, MAP3K3, MAP3K5, MAP3K10, and MAP3K15 were upregulated in HCC tumor tissues, whereas MAP3K7, MAP3K8, MAP3K9, and MAP3K11 were downregulated in tumor tissues in GSE14520." (PMID 35311629, 2022). "Our analysis showed that patients with high MAP3K7 expression in the tumor had shorter overall and progression free survival." (PMID 34676048, 2021). "Third, MAP3K7 expression was higher in tumor tissues, and high MAP3K7 expression, alone or in combination with its downstream regulator mTOR, was associated with poor survival in patients with HCC." (PMID 31214512, 2019). "Stable knockdown of MAP3K7 attenuated tumor formation in a spheroid cell culture model and tumor xenograft mouse model." (PMID 31214512, 2019). "Genetic and pharmacological targeting of MAP3K7 attenuated tumor cell growth in spheroid cell culture and a xenograft mouse model." (PMID 31214512, 2019). "Typical examples included known or putative tumor suppressors, such as NF1, DICER1, PML, PDS5A, MAP3K7, and PPP2R5A, in which SF3B1 mutation resulted in usage of alternative 3′ splice sites." (PMID 30194306, 2018). "In contrast, inhibition of MAP3K7 in breast cancer cells reduced tumor growth and impaired metastasis." (PMID 29914415, 2018). "This 6q12-22 area contains several genes with a known or suspected tumor-suppressing function including MAP3K7, for which a tumor-suppressive role for prostate epithelial cells has recently been demonstrated." (PMID 28385156, 2017). "The data also suggest that presence of a 6q15 deletion including MAP3K7 - either directly or indirectly - prevents tumor cells from developing TMPRSS2:ERG fusions." (PMID 26684029, 2016). "Although the precise function of MAP3K7 remains obscure, our work along with previous works characterize it as a tumor promoter in a similar manner to other members of the MAP3K family." (PMID 25889255, 2015).
tumor (continued). "On one hand, tumor-intrinsic epigenetic factors such as SIRT1, CHD1, and MAP3K7 can determine whether a tumor is permissive or resistant to VSV infection, making them promising biomarkers for patient stratification." (PMID 41294689, 2025). "Consistent with subcutaneous model, Map3k7-silenced tumors were reduced in weight, infiltrated with more total and activated effector (CD44highKi-67+) CD4+ and CD8+ T cells, and less tumor associated macrophages (TAMs), which were more M1-polarized." (PMID 41280086, 2025). "The level of MAP3K7 protein was higher in tumor tissues than in tumor adjacent normal tissues (p < 0.0001), while the level of MAP3K7 protein was slightly higher in metastatic tumor tissues than in primary tumor tissues." (PMID 31214512, 2019). "However, MAP3K7 can serve as a tumor promoter or suppressor in liver cells, which is still controversial." (PMID 31214512, 2019). "High MAP3K7 protein level in tumor tissues had poor overall survival." (PMID 31214512, 2019). "Thus, we inspected the involvement of the potential downstream effector mTOR in MAP3K7-modulated tumor malignancy in HCC cells." (PMID 31214512, 2019). "In this study, we found that tumours infiltrating the extraprostatic space, in contrast to intraprostatic tumours, closely resemble the aggressive S3 molecular signature, lack the S2 signature, and show decreased expression of genes located at the 6q12-22 locus, including MAP3K7." (PMID 39796635, 2024). "Besides, rescue experiments revealed that miR-143-3p could change proliferation, migration and invasion capabilities of tumor cells by interacting with MAP3K7 and exhibit regulative effects on GC." (PMID 32647147, 2020). "Likewise, tumor weight was significantly lower in MAP3K7-silenced HCC tumors." (PMID 31214512, 2019). "However, the levels of Cx62 mRNA from the ONCOMINE database were comparable between tumor samples and normal controls, suggesting that another transcript located in this deleted segment such as MAP3K7 might have tumor suppressive actions." (PMID 25018732, 2014). "(A–C) RT-qPCR data showing Map3k7 expression in KPC (n=13) and KPC-Sf3b1K700E/+ (n=12) ex vivo tumor cultures (A), as well as WT (n=3) and Sf3b1K700E/+ (n=4) pancreata (B) and organoid lines (C)." (PMID 37823551, 2023). "(E) Representative gel image (top) and NGS-results (bottom) of Map3k7 cDNA isolated from sorted KPC (n=3) and KPC-Sf3b1K700E/+ tumor cells (n=4)." (PMID 37823551, 2023). "The differential analysis in normal breast tissue and tumor tissue revealed that, except for RIPK1, RIPK3, TNF, MAP3K7, and STAT3, all the other genes showed significantly differential expression in BRCA." (PMID 35686108, 2022). "NUMB, VCL, MAP3K7 and EXOC1 exon skipping events are examples of known splicing events that can be also observed in tumor tissue." (PMID 36304260, 2022). "MAP3K7 requires TAK1-binding protein 1 (TAB1), TAB2, and TAB3 to trigger NF-κB activation, which is a key transcription factor for tumor initiation and malignancy." (PMID 31214512, 2019). "A larger and significant decrease in tumor volume is found when CK2α siRNA is used in combination with PAK7 and/or MAP3K7 siRNAs." (PMID 28134850, 2017). "The tumor volume was further decreased when co-silenced with the WNT activator, PAK7, or MAP3K7." (PMID 39221276, 2024). "Furthermore, an analysis of genes impacted by somatic copy number alterations unveiled a heightened occurrence of deletions in tumor suppressor genes, such as RB1, PTEN, and MAP3K7, among different LGG patients (all p < 0.05)." (PMID 37660060, 2023).
tumor (continued). "We confirmed an aberrant increase of cassette exon skipping in tumor specimens for PACSIN2 exon 8, DIAPH1 exon 2, FGFR1OP2 exon 4, MARK3 exon 16, DST exon 93, LMO7 exon 10, and RBM5 exon 7, whereas ADD3 exon 13, MAP3K7 exon 12, and MARK2 exon 15 were preferentially included in tumor specimens." (PMID 34202984, 2021). "The level of MAP3K7 protein was reduced in MAP3K7-silenced tumors, confirming that HCC cells lacking MAP3K7 exhibited arrested tumor growth in vivo." (PMID 31214512, 2019). "Deletions in MAP3K7 have recently been associated with early PSA recurrence, and in tumours that do not contain the TMPRSS2-ERG gene fusion, a tumour-suppressor role for MAP3K7 has been proposed." (PMID 26501111, 2015). "However, we focused our attention on PACSIN2, DIAPH1, MARK3, ADD3, MAP3K7, and MARK2 cassette exons as these events were validated in both normal and cancer cell lines and in non-pathological and tumor breast specimens." (PMID 34202984, 2021).
cancer (33 papers, 2013 to 2026). A tumor composed of atypical neoplastic, often pleomorphic cells that invade other tissues. "CHD1 and MAP3K7 are recurrently mutated in cancer, and reduced expression in tumors correlates with response to immune checkpoint inhibitors in patients, nominating these genes as potential biomarkers of immunotherapy response." (PMID 41564866, 2026). "Intriguingly, 17 out of 24 cancer types shared the correlation pattern, indicating that they have a common mechanism underlying the AS of MAP3K7." (PMID 36473963, 2022). "MAP3K7 has been considered to be an important regulator of many cellular pathways associated with cancer cell growth." (PMID 28746466, 2017). "MAP3K7 is a component of the TGF-β signalling pathway that has been implicated in cancer and EMT, although its effects vary." (PMID 27876705, 2016). "The TGF-β and BMP activated kinase MAP3K7 is essential for a series of cancer associated signaling pathways like the p38 and JNK." (PMID 26684029, 2016). "Notably, for all the seven HUB nodes of the linking region between three cancer networks, mutations were found in all three cancers (BlC, KiC, PrC) with the higher frequency percentages identified for four nodes: MAP3K7, NR3C1, PABPC1 and CTNNB1." (PMID 29991691, 2018). "Most cancer cell lines (>90%) are unaffected by MAP3K7 depletion, assessed by a DepMap gene dependency score above −0.5, in contrast to common essential gene MCM2." (PMID 38632238, 2024). "We analyzed a subtype-specific AS in exon 11 of mitogen-activated protein kinase kinase 7 (MAP3K7) as an example of a pan-cancer AS biomarker." (PMID 36473963, 2022). "The ES event in MAP3K7 gene (exon 11) was represented in this study as a potential pan-cancer AS biomarker capable of discriminating molecular subtypes in 10 cancer types." (PMID 36473963, 2022). "Five cryptically spliced genes (ANKHD1, ATM, FOXP1, MAP3K7, and TTI1), identified in previous transcriptomic analyses in SF3B1-mutated patients, were analyzed in different cancer types." (PMID 33585229, 2020). "Similar observations in different cancer models have primarily been attributed to an inactivation of the NF-κB pathway upon MAP3K7 inhibition." (PMID 29914415, 2018). "In ERG-negative cancer, high levels of BCAR1 expression were significantly linked to presence of deletions of PTEN (p < 0.0001), CHD1 (5q21) (p < 0.0001) and MAP3K7 (6q15) (p < 0.0001), while these associations were lost in ERG-positive cancer." (PMID 29304771, 2018). "In a recent study, we found a strong association of MAP3K7 deletion with early PSA recurrence in a series of 2,289 cancers analyzed by FISH." (PMID 26684029, 2016). "Despite the generally low PSI values for the 325 cryptic 3’SSs from the CLL-only analysis, we identified four genes previously implicated in cancer (TTI1, MAP3K7, FXYD5, PFDN5) and six others (YIF1A, ORAI2, ZNF91, ZNF548, RP11–1280I22." (PMID 25768983, 2015). "Additionally, we analyzed the linear relationship between PANRGs and miRNA and found that MAP3K7 correlates to many miRNAs in most cancers." (PMID 38002938, 2023). "Taken together, these data support that an ES event in exon 11 of MAP3K7 may play a role in regulating subtypes across diverse cancers, and that this event may particularly play a crucial role in STAD, where its function has not been reported earlier." (PMID 36473963, 2022). "Down-regulated MAP3K7 has been reported to promote cancer cell death in BC." (PMID 28746466, 2017). "A MAP3K7 deletion was found in 165 (17.8%) of 924 cancers spots." (PMID 26684029, 2016). "The prognosis-associated PANoptosis-related genes (ZBP1, MAP3K7, and RBCK1) were highly elevated in the low-risk group and less expressed in the high-risk group, suggesting the participation of PANoptosis in cancer progression and as a potential target for therapeutic intervention in cancers." (PMID 38169587, 2024).
cancer (continued). "Upstream sensors like ZBP1, AIM2, and RIPK1, along with regulators identified in cancer-related PANoptosis studies, such as IRF1, ADAR, MAP3K7, and NFS1, were also incorporated for their significant regulatory roles." (PMID 39901195, 2025). "This chromosomal region includes the mitogen-activated protein kinase kinase kinase 7 (MAP3K7) gene which has a crucial role in innate immune signaling and was observed to be functionally and prognostically relevant in different cancer entities." (PMID 29914415, 2018). "To find a possible link between these three cancers subjected to arsenicals exposure, we merged the three networks and identified seven HUB nodes (RXRA, MAP3K7, NR3C1, PABPC1, NDRG1, RELA and CTNNB1) of the linking region between three cancer networks." (PMID 29991691, 2018). "Depending on the sequel of development of MAP3K7 deletions and ERG-expression, one can expect a small area of cancer having both alterations within a larger area having only the first one of these changes." (PMID 26684029, 2016). "The same MAP3K7 targeting sgRNAs did not affect growth in immortalized human fibroblasts (BJ hTERT) or retinal pigmental epithelial cells (RPE-1 hTERT) nor in other cancer cell lines." (PMID 38632238, 2024). "Upon stimulation of proinflammatory cytokines, the MAP3K7–IKK signaling axis activates the transcription factor NF-kB, which regulates pro-survival genes and PD-L1 mRNA expression in various cancer types (including PC), probably favoring cancer immune escape." (PMID 35203446, 2022). "Nevertheless, since these results have been reported previously in cancer cells and MAP3K7 was selected from our screen in regular medium without TNF-α stimulation, we set them aside." (PMID 31214512, 2019). "Gene silencing of MAP3K7 enhances the sensitivity of cancer cells, but not normal epithelial cells, to chemotherapeutic drugs." (PMID 31214512, 2019). "For instance, MAP3K7 controls a variety of cell functions including transcription regulation and apoptosis through mediating the signaling transduction induced by TGFβ and bone morphogenetic protein (BMP) in a broad range of cancers." (PMID 27769251, 2016).